CYP4V2 (cytochrome P450 family 4 subfamily V member 2)
Diseases named in the same sentence as CYP4V2 in open-access papers:
CYP4V2 is named in the same sentence as 40 diseases in open-access papers, as found by Europe PMC text mining. Sharing a sentence is not in itself a finding about the gene and the disease. The quoted sentences say what the papers report.
Bietti crystalline dystrophy (30 papers, 2011 to 2026). "Bietti crystalline corneoretinal dystrophy is an inherited retinal disease caused by mutations in CYP4V2, which results in blindness in the working-age population, and there is currently no available treatment." (PMID 38653979, 2024). "Mutations in CYP4V2 are the main cause for Bietti’s crystalline dystrophy, an inherited disease of the retina." (PMID 37601072, 2023). "Another missense mutation; c.332T > C; p.(Ile111Thr) in CYP4V2 showed a high prevalence in Lebanese individuals with Bietti crystalline dystrophy." (PMID 37127645, 2023). "Variants in CYP4V2 are related to the occurrence of deep vein thrombosis and Bietti corneoretinal crystalline dystrophy." (PMID 36437455, 2022). "CYP4V2, as a causative gene for Bietti’s Crystalline Dystrophy, belongs to the cytochrome P450 superfamily and encodes fatty acid ω-hydroxylase for both saturated and unsaturated fatty acids." (PMID 35351103, 2022). "Bietti crystalline dystrophy is primarily a retinal dystrophy caused by a CYP4V2 mutation and typically presents with crystalline retinal deposits in the posterior fundus." (PMID 36320086, 2022). "Bietti crystalline dystrophy is primarily a retinal dystrophy caused by a CYP4V2 mutation and is presumed to affect fatty-acid omega-hydroxylase activity in retinal pigmented epithelium and accumulation of yellow-white crystalline-like deposits." (PMID 36320086, 2022). "Bietti crystalline dystrophy is a typically autosomal recessive disorder caused by mutations in the CYP4V2 gene that result in defective ocular fatty acid metabolism in retinal pigment epithelium and the formation of crystalline deposits." (PMID 36320086, 2022). "CYP4V2 variants were responsible for an even larger portion of our cohort (12 families, 6.7% of solved families); all affected patients had Bietti crystalline dystrophy, exclusively." (PMID 33608557, 2021). "The rare form of retinal dystrophy, Bietti crystalline dystrophy, is associated with variations in CYP4V2, a member of the cytochrome P450 family." (PMID 34068831, 2021). "Bietti crystalline dystrophy (BCD) (OMIM#210370) is a severe inherited retinal dystrophy that is caused by autosomal recessive mutations in the cytochrome P450 family 4 subfamily V member 2 (CYP4V2) gene." (PMID 33541298, 2021). "CYP4V2 is widely expressed in the liver and ophthalmic tissues and CYP4V2 defect has been linked to ophthalmic diseases, such as Bietti’s crystalline dystrophy." (PMID 31480463, 2019). "For example, the human homolog of the age down-regulated gene Cyp4c3, CYP4V2, is associated with a recessive inherited retinal disorder, Bietti crystalline corneoretinal dystrophy that involves progressive age-associated retinal dystrophy." (PMID 29162050, 2017). "We identified eight different CYP4V2 mutations in 10/19 patients in our cohort of crystalline retinal dystrophies, clinically diagnosed as Bietti crystalline dystrophy." (PMID 25629076, 2015). "Bietti's crystalline dystrophy (BCD) is likely related to aberrant oxidation of cellular lipid metabolism which is caused by mutations of the CYP4V2 gene, a member of the cytochrome P450 genes, and the dystrophy can be familial." (PMID 24949209, 2014). "The purpose of this study was to determine the retinal morphology of eyes with Bietti crystalline dystrophy (BCD) associated with a CYP4V2 mutation using high-resolution imaging techniques." (PMID 25276414, 2014). "Mutations of the gene encoding CYP4V2 have been associated with Bietti Crystalline Corneoretinal Dystrophy and the protein has recently been characterised as a fatty acid {omega}-hydroxylase." (PMID 22348077, 2012). "Bietti crystalline dystrophy is caused by mutations in the cytochrome p450, family 4, subfamily v, polypeptide 2 (CYP4V2) gene, which belongs to the cytochrome P450 family of genes in chromosome 4q35." (PMID 21850171, 2011).
Bietti crystalline dystrophy (continued). "Bietti crystalline dystrophy (BCD) is a hereditary retinal disease caused by loss-of-function mutations in the CYP4V2 gene." (PMID 42123783, 2026). "Bietti crystalline dystrophy (BCD) is an inherited retinal degeneration disease caused by mutations in the CYP4V2 gene." (PMID 38992691, 2024). "CYP4V2 stands apart from the P450s 2C8, 2J2, 2U1, 4A, and 4B1 as mutations in its gene cause Bietti crystalline dystrophy (BCD), a rare autosomal recessive disease." (PMID 36914277, 2023). "Bietti crystalline dystrophy (BCD) is an inherited retinal disease (IRD) caused by mutations in the CYP4V2 gene." (PMID 35680963, 2022). "Now, it is well established that Bietti crystalline dystrophy (BCD) is caused by mutations of the CYP4V2 gene." (PMID 25505979, 2014). "Mutation profile of CYP4V2 in Bietti crystalline dystrophy (BCD) patient cohort." (PMID 21850171, 2011). "Bietti crystalline corneoretinal dystrophy (BCD) is a rare autosomal recessive disorder, mainly affecting Asian populations, particularly Chinese and Japanese, caused by mutations in CYP4V2, a member of the cytochrome P450 family 4 involved in fatty acid metabolism." (PMID 36675224, 2023). "Bietti crystalline dystrophy (BCD) is a rare autosomal recessive disorder caused by mutation of the cytochrome P450, family 4, subfamily V, polypeptide 2 (CYP4V2) gene and characterized by retinal pigmentary abnormalities and scattered deposits of crystals in the retina and the marginal cornea." (PMID 22605929, 2012). "Bietti crystalline dystrophy (BCD), also known as Bietti crystalline corneoretinal dystrophy (OMIM 210370), is an autosomal recessive retinal degenerative disorder caused by mutations in the CYP4V2 gene." (PMID 39171529, 2024).
Retinal dystrophy (6 papers, 2015 to 2022). Retinal dystrophy is an abnormality of the retina associated with a hereditary process. "For example, previous studies have associated OGN with bone and muscle formation and CYP4V2 is associated in man with retinal dystrophy." (PMID 27507242, 2016).
retinal disease (5 papers, 2013 to 2026). "CYP-31A2 is a class 4 cytochrome P450 that is most similar to human CYP4V2, which is implicated in the retinal disease Bietti's Crystalline Dystrophy." (PMID 23382703, 2013).
retinitis pigmentosa (4 papers, 2012 to 2024). Retinitis pigmentosa (RP) is an inherited retinal dystrophy leading to progressive loss of the photoreceptors and retinal pigment epithelium and resulting in blindness usually after several decades. "The crystallized retinitis pigmentosa (BCD) of the probands is different from the BCD manifestation caused by the typical CYP4V2 gene mutation." (PMID 32100970, 2020).
venous thromboembolism (4 papers, 2019 to 2023). Occlusion of the lumen of a vein by a thrombus that has migrated from a distal site via the blood stream. "For example, a recent study has found that CYP4V2-rs13146272 is closely linked to the occurrence of venous thromboembolism (VTE)." (PMID 38066650, 2023). "A meta-analysis has demonstrated that CYP4V2 genetic variants are the risk factors for venous thromboembolism." (PMID 36437455, 2022). "Genome-wide association studies have identified the CYP4V2 polymorphism (rs13146272) as a risk factor associated with venous thromboembolism (VTE)." (PMID 30276487, 2019). "CYP4 subfamily V member 2 (CYP4V2) polymorphisms are related to venous thromboembolism." (PMID 36437455, 2022). "Moreover, a role of CYP4V2 in ischemic stroke due to venous thromboembolism has been shown." (PMID 37601072, 2023).
deep vein thrombosis (3 papers, 2013 to 2022). "The exact mechanism through which the CYP4V2 gene defect increases the risk of deep vein thrombosis remains poorly understood." (PMID 31480463, 2019). "In addition to BCD, genome-wide analysis found that a CYP4V2 genetic variant was strongly associated with deep vein thrombosis, which was confirmed later in multiple studies." (PMID 31480463, 2019). "In the present study, we searched for evidence for the existence of common regulatory elements within a locus that has been linked to deep vein thrombosis and harbors F11, KLKB1 and CYP4V2 i.e. the 4q35.2 locus." (PMID 24066149, 2013).
dyslipidemia (3 papers, 2019 to 2025). "This important observation was further supported by evidence in Cyp4v3 (mouse ortholog) knockout mice (Cyp4v3−/−) and patients with mutations in CYP4V2 (human ortholog) where a systemic dyslipidemia and a decreased metabolism of labeled fatty acid were detected." (PMID 30861021, 2019). "Several biochemical findings have revealed systemic abnormalities of lipid metabolism in patients with BCD, and alterations in functional CYP4V2 are thought to cause impaired lipid processing in the RPE layer, leading to severe localized dyslipidemia and photoreceptor degeneration." (PMID 40097952, 2025).
Venous thrombosis (3 papers, 2013 to 2023). Formation of a blood clot (thrombus) inside a vein, causing the obstruction of blood flow. "Multiple studies on CYP4V2 polymorphisms have revealed the relationship between rs13146272 and venous thrombosis." (PMID 38066650, 2023). "Association of the genetic variant 7234C>A (rs13146272) on exon 6 of the CYP4V2 gene with the risk of deep venous thrombosis and tamoxifen-induced venous thrombosis has been reported." (PMID 31480463, 2019). "Single nucleotide polymorphisms (SNPs) in a 4q35.2 locus that harbors the coagulation factor XI (F11), prekallikrein (KLKB1), and a cytochrome P450 family member (CYP4V2) genes are associated with deep venous thrombosis (DVT)." (PMID 24066149, 2013).
Atrophy (2 papers, 2022 to 2025). Any weakening or degeneration, especially through lack of use. "Deficiency of another RP-associated gene, CYP4V2, results in RPE lipid accumulation, which precedes RPE atrophy and photoreceptor degeneration." (PMID 41288322, 2025). "The yellow-white crystalline deposits are caused by the abnormal expression of the CYP4V2 gene in the human retina and RPE, which decreases with the deterioration of the retina and RPE atrophy." (PMID 35655804, 2022).
ischemic stroke (2 papers, 2022 to 2023). A stroke disorder caused by obstruction of blood flow to the brain, due to thrombotic (local blood clot formation) or embolic (due to a blood clot or other material traveling from another site) event. "However, the influence of CYP4V2 polymorphisms on the susceptibility to ischemic stroke (IS) remains undetermined." (PMID 36437455, 2022).
Stroke (2 papers, 2020 to 2022). Sudden impairment of blood flow to a part of the brain due to occlusion or rupture of an artery to the brain. "It will be interesting to study whether CYP4V2 rs1398007 is related to other stroke subtypes." (PMID 36437455, 2022). "Although the discussion was mainly focused on the gene SP1 that presented significant expression change in the case of stroke, other genes with minor expression variances may also worth a closer look, including PF4 (LFC: 0.79; p-value< 10–3), CYP4V2(LFC: 0.72; p-value = 0.046)." (PMID 33092540, 2020).
amyloidosis (1 paper, 2021). A disorder characterized by the localized or diffuse accumulation of amyloid protein in various anatomic sites. "Although the role of CYP4V2 in amyloidosis is currently unclear, activated TLR3, along with some members of the toll-like receptors family, can induce Aβ uptake or inflammatory response during the AD progression." (PMID 30361487, 2021).
atherosclerosis (1 paper, 2021). A disease characterized by the build-up of fatty material and calcium deposition in the arterial wall resulting in partial or complete occlusion of the arterial lumen. "Furthermore, the KLKB1/CYP4V2 locus has been associated with atherosclerosis, and the KLKB1 and F12 genes are both involved in several proteolytic reaction cascades in the cardiovascular system." (PMID 33961016, 2021).
cervical carcinoma (1 paper, 2013). A carcinoma arising from either the exocervical squamous epithelium or the endocervical glandular epithelium. "The effect of ectopic expression of SORBS2, TLR3, CYP4V2, FBXO18, IL15RA, WDR37 and DIP2C on the cell phenotype, in particular senescence, was investigated in primary cells, HPV-immortalized cells and cervical carcinoma cells." (PMID 24165198, 2013).
chorioretinal degeneration (1 paper, 2021). "In the case of a 52-year-old woman showing diffuse chorioretinal degeneration, we found an associated Bietti crystalline dystrophy (BCD) caused by CYP4V2." (PMID 33946315, 2021).
choroidal neovascularization (1 paper, 2011). An eye disorder described by the growth of new blood vessels that originate from the choroid through a break in the Bruch membrane into the sub–retinal pigment epithelium (sub-RPE) or subretinal space. "In the present study, we report on two patients with BCD and subfoveal choroidal neovascularization with CYP4V2 screening results." (PMID 21850171, 2011).
corneal dystrophy disease (1 paper, 2019). "CYP4V2, located on chromosome region 4q35 and on genes that are involved in coagulation, was reported to be associated with corneal dystrophy disease and lipid metabolism." (PMID 30276487, 2019).
coronary heart disease (1 paper, 2023). "The research aimed to detect the association between single nucleotide polymorphisms (SNPs) in CYP4V2 gene and coronary heart disease (CHD) risk." (PMID 38066650, 2023).
Crohn disease (1 paper, 2021). A gastrointestinal disorder characterized by chronic inflammation involving all layers of the intestinal wall, noncaseating granulomas affecting the intestinal wall and regional lymph nodes, and transmural fibrosis. "Some ICGs, such as BDH2, CYP4V2, OIT3, PLD1 and SLC25A23, were reported as differentially expressed in ileum tissue from Crohn’s disease vs. non-inflammatory bowel disease control." (PMID 34098982, 2021).
diabetes (1 paper, 2022). "An expression quantitative trait loci (eQTL) laser capture microdissection (LCM) analysis of iT2DMts from phenotyped pancreatectomized patients (PPPs) identified that CYP4V2 is associated with the levels of glycated hemoglobin A1c (HbA1c), which plays a key role in the management of diabetes." (PMID 36131924, 2022).
familial hypertrophic cardiomyopathy (1 paper, 2013). Hypertrophic cardiomyopathy caused by mutations in the genes encoding components of the sarcomere, in the absence of predisposing conditions. "Specifically SLC25A4 is connected with progressive external ophthalmoplegia and familial hypertrophic cardiomyopathy, TLR-3 with susceptibility or resistance to some kinds of infections, F11 with deficiency in coagulation factor XI and CYP4V2 with Bietti crystalline corneoretinal dystrophy." (PMID 24176130, 2013).
Hepatic steatosis (1 paper, 2024). Steatosis is a term used to denote lipid accumulation within hepatocytes. "Prior studies demonstrate that CYP4v2 promotes lipogenesis and oxidative respiration but prevents oxidative stress and the conversion of hepatic steatosis to MASH." (PMID 39228797, 2024).
hepatocellular carcinoma (1 paper, 2019). A malignant tumor that arises from hepatocytes. "Evaluation of the CYP4 expression profile in hepatocellular carcinoma (HCC) showed that CYP4F2, CYP4F12, and CYP4V2 mRNA levels were negatively correlated with cell-cycle-associated genes, suggesting that these CYP4 genes are favorable prognostic factors in HCC." (PMID 31480463, 2019).
Hypertension (1 paper, 2022). The presence of chronic increased pressure in the systemic arterial system. "The relationship between CYP4V2 SNPs and IS risk in IS patients with or without hypertension compared with healthy controls was also assessed." (PMID 36437455, 2022).
macular holes (1 paper, 2014). A hole in the macula of the retina. "We identified five mutations in CYP4V2, and characterized the clinical and genetic features of two atypical forms of BCD, including BCD associated with CNV and BCD associated with a macular hole." (PMID 24739949, 2014).
occult macular dystrophy (1 paper, 2021). "This is reasonable when we correlate the clinical phenotypes; CEP290 is related to LCA, RP1L1 is related to occult macular dystrophy (OMD), ABCA4 is related to Stargardt disease and severe forms of autosomal recessive RP, and CYP4V2 is related to BCD." (PMID 33608557, 2021).
retinal degeneration (1 paper, 2023). Degeneration of the retina. "BCD is a rare blinding disease caused by severe retinal degeneration and mutations in the CYP4V2 gene." (PMID 36658594, 2023).
schizophrenia (1 paper, 2025). A major psychotic disorder characterized by abnormalities in the perception or expression of reality. "Interestingly, we identified genes associated with fatty acid metabolism amongst VMPs with concordant changes in blood and brain, including HSD17B4, CYP4V2, FADS2, and SCD, indicating altered DNA methylation variance may impact fatty acid metabolism in these tissues in schizophrenia." (PMID 39271751, 2025).
Sepsis (1 paper, 2023). Sepsis is defined as life-threatening organ dysfunction caused by a dysregulated host response to infection. "Except for CYP4V2, there were also three genes down-regulated in sepsis, including ALOX15, BCL2, and FTO." (PMID 36820206, 2023). "Further ROC analysis suggested that the AUC of GCLM, LCN2, LTF, and CYP4V2 in diagnosis between severe forms and mild forms of sepsis were all >0.65." (PMID 36820206, 2023). "CYP1B1 was found to be up-regulated simultaneously in sepsis vs healthy controls, sepsis vs non-infection disease, and sepsis vs uncomplicated infections, while CYP4V2 was down-regulated simultaneously in sepsis vs healthy controls, sepsis shock vs sepsis, and severe sepsis vs mild sepsis." (PMID 36820206, 2023). "In our results, two cytochromes were identified as DEGs in sepsis P450, CYP1B1, and CYP4V2." (PMID 36820206, 2023). "Additionally, when compared to sepsis shock, we found TPSO, GCLM, CYP1B1, LCN2, and LTF were up-regulated and the FTO and CYP4V2 were down-regulated in the sepsis (p < 0.05)." (PMID 36820206, 2023).
steatosis (1 paper, 2024). Increased lipid within the cytoplasm of cells. "In human patients, the CYP4F12, CYP4F22, and CYP4V2 mRNA levels increase in steatosis and MASH, while the levels of CYP4B1, CYP4X1, and CYPZ1 mRNAs decrease in steatosis and MASH while the mRNA for these genes increases in HCC." (PMID 40452921, 2024).
tumor (2 papers, 2021 to 2025). "A positive correlation with increasing tumour grade has been observed with the expression of CYP4V2, CYP4X1 and CYP4Z1; while CYP1B1, CYP3A5 and CYP51 were significantly associated with the ER status of the tumour." (PMID 33809117, 2021). "The results indicated that CYP4V2, CYP4X1, and CYP4Z1 expression were correlated with a higher tumor grade." (PMID 40723371, 2025). "The results showed that CYP4V2, CYP4X1, and CYP4Z1 expression correlated with a higher tumor grade." (PMID 40723371, 2025).
immune diseases (1 paper, 2021). "Interestingly, 54 genes within the 29 mQTL loci we identified have been reported to be candidates for metabolic drug targets (e.g., CYP4V2) in relevant immune diseases, and further validation of their potential as therapeutic targets is warranted." (PMID 34229738, 2021).
CYP4V2 also shares sentences with these, for which no sentence is quoted: Bietti crystalline corneoretinal dystrophy (7 papers); Blindness (2); autosomal dominant retinitis pigmentosa (1); inflammatory bowel disease (1); osteoporosis (1); progressive external ophthalmoplegia (1); retinal disorder (1); Stargardt disease (1).